MESTIT1 (MEST intronic transcript 1, antisense RNA)
Synonyms: NCRNA00040; MEST-AS1; MEST-IT; MEST-IT1; PEG1-AS
Gene: Long non-coding RNA gene on chromosome 7 (130,486,042 to 130,491,033, reverse strand). Ensembl gene ENSG00000272701.
Diseases named in the same sentence as MESTIT1 in open-access papers:
MESTIT1 is named in the same sentence as 7 diseases in open-access papers, as found by Europe PMC text mining. Sharing a sentence is not in itself a finding about the gene and the disease. The quoted sentences say what the papers report.
breast carcinoma (2 papers, 2021 to 2023). "In turn, MESTIT1 is likely a protective factor in breast cancer and a risk factor in prostate cancer." (PMID 38003837, 2023). "Overexpressed miR-93 in MCF-7 breast cancer cells was associated with suppressed expression of multiple lncRNAs, and these downregulated lncRNAs (MESTIT1, LOC100128164, and DNMBP-AS1) were significantly associated with poor overall survival in breast cancer patients." (PMID 34220926, 2021). "MiR-200c-3p, miR-204-5p, miR-20b-5p, miR-7-1-3p, miR-105-5p, miR-342-3p, DNMBP-AS1, HPN-AS1, LINC00461, LINC00472, LINC00667, LOC100128164, LOC284578, MESTIT1, RHPN1-AS1, and SLC26A4-AS1 were significantly associated with breast cancer patients’ overall survival (log-rank P < 0.05)." (PMID 34220926, 2021). "We also observed that 6 miRNAs (miR-7-1-3p, miR-20b-5p, miR-105-5p, miR-200c-3p, miR-204-5p, and miR-342-3p) and 10 lncRNA (DNMBP-AS1, HPN-AS1, LINC00461, LINC00472, LINC00667, LOC100128164, LOC284578, MESTIT1, RHPN1-AS1, and SLC26A4-AS1) can predict overall survival of patients with breast cancer." (PMID 34220926, 2021).
cognitive disease (1 paper, 2022). "The MESTIT1 gene is associated with a cognitive disease, as reported in89." (PMID 35705654, 2022).
lung neoplasm (1 paper, 2013). A benign or malignant, primary or metastatic neoplasm involving the lungs. "On the other hand, long arm of chromosome 7 possesses imprinted domain in 7q32-qter which including MEST1, MESTIT1, COPG2IT1loci and a group of four carboxypeptidase A (CPA) genes (CPA1, CPA2, CPA4, CPA5), which are seem to be important (mainly MEST) in the initiation of breast and lung neoplasms." (PMID 23288724, 2013).
cancer (1 paper, 2023). A tumor composed of atypical neoplastic, often pleomorphic cells that invade other tissues. "Moreover, the most up-regulated lncRNA genes found in the infected samples—MYRF-AS1, ATP2A1-AS1, CTC-338M12.4, MESTIT1, PRANCR, and SLC25A5-AS1—are associated with several types of cancers in a conflicting manner." (PMID 38003837, 2023).
MESTIT1 also shares sentences with these, for which no sentence is quoted: infertile (1 paper); male infertility (1); prostate carcinoma (1).